PARP14 (poly(ADP-ribose) polymerase family member 14)
Diseases named in the same sentence as PARP14 in open-access papers (continued):
Sharing a sentence is not in itself a finding about the gene and the disease.
tumor (32 papers, 2014 to 2026). "Notably, PARP14 is highly expressed in HCC primary tumours and associated with poor patient prognosis." (PMID 26258887, 2015). "Considering the mostly cancer-promoting effect of tumor-associated macrophages (TAMs), which have a “tumor-friendly”, M2-like phenotype, inhibitors of PARP-14 may have the potential to reverse M2 polarization of TAM, similar to models of IL-4-induced M2 polarization." (PMID 33923319, 2021). "Mechanistically, the PARP9–DTX3L complex post-transcriptionally regulates PARP14, contributing to tumor cell survival." (PMID 40741921, 2025). "PARP14 can enhance the inflammatory response by supporting the polarization of macrophages to the tumor-promoting M2 type, and, thus, promote the occurrence and development of multiple tumors, such as breast cancer." (PMID 41460301, 2025). "PARP14 and PARP16 inhibitors: The effect of inhibiting PARP14 on metabolic reprogramming phenomena in tumor models in response to energy stress." (PMID 41463260, 2025). "These new products have further increased their specificity for other tumor-targeting MARTs, such as PARP14 and PARP15." (PMID 41463260, 2025). "In contrast, such PARP-immune gene co-expression was not evident in normal adjacent tissue samples displaying only a weak positive correlation between PARP14 and IFIT1 expression after CRT, suggesting a tumor tissue-specific association." (PMID 40646573, 2025). "Gene expression profiling confirmed increased expression levels of other members of the ARTD family including Parp9, Parp10, Parp12 and Parp14 in Parp7KO tumours." (PMID 39867896, 2024). "This implies that either decreasing STAT1 activity by JAKi to block expression of immunosuppressive molecules (including PARP14) or boosting STAT1 by PARP14i to enhance tumour immunogenicity are both viable approaches to increasing response to α-PD-1 therapy." (PMID 37752135, 2023). "We made similar observations for Stat1 and other STAT1 target genes including Irf1, Cxcl10, and Cxcl11, which suggested that PARP14 was induced specifically in IFNγ-inflamed tumours but independently of α-PD-1." (PMID 37752135, 2023). "RBN012759, a newly developed selective PARP14 inhibitor focused on PARP14’s role in immunotherapy, has shown a reversion of IL-4-directed pro-tumor genes, indicating the potential to employ the inhibitor as an anticancer therapeutic." (PMID 37508568, 2023). "To address the contribution of PARP14 expression in tumour cells to mediating α-PD-1 resistance, we expressed short-hairpin (sh) RNA targeting PARP14 (shPARP14) for RNA interference-mediated down-regulation in YUMM2.1 and MC38 cells." (PMID 37752135, 2023). "In agreement with PARP14 being an IFNγ target gene, we observed PARP14 levels increasing in response to higher doses of IFNγ in multiple human and mouse tumour cell lines." (PMID 37752135, 2023). "PARP14 inactivation in macrophages promotes the pro-inflammatory phenotype of macrophages which stimulates anti-tumor response." (PMID 36814782, 2023). "The effect of chronic IFNγ exposure on and possible contribution of PARP14 to tumour infiltration by myeloid and helper T cell populations also merits further investigation." (PMID 37752135, 2023). "We explored the effects of IFNγ preconditioning and PARP14 depletion on the composition and activation status of the tumour immune infiltrate." (PMID 37752135, 2023). "For instance, PARP14 demonstrated important roles in DNA damage response, T-cell development, macrophage activation and tumor development." (PMID 37163422, 2023). "The proteins encoded by PARP14 and PARP9 are DNA damage repair enzymes that act as tumor suppressors by consuming NAD+ to stabilize cell metabolism and prevent genomic instability from containing potential oncogenic mutations." (PMID 38186577, 2023).
tumor (continued). "In this work, we investigate IFNγ-driven reprogramming of gene expression in tumour cells associated with acquired resistance to ICBT, therein demonstrating a role for the IFNγ target gene product poly-ADP ribosyl polymerase 14 (PARP14)." (PMID 37752135, 2023). "Since the RB pathway is a tumor suppressor pathway, this suggests a role for PARP14 in modulating tumor progression." (PMID 36814782, 2023). "PARP14 promotes aerobic glycolysis or the Warburg effect, used by the majority of tumor cells, by inhibiting pro-apoptotic kinase JNK1." (PMID 29284484, 2017). "In human fibrosarcoma cells, PARP14 was shown to regulate the abundance of phosphoglucose isomerase, a glycolytic enzyme involved in tumour aggressiveness." (PMID 26258887, 2015). "Next, we subcutaneously injected Huh7 cells bearing PARP14 or NS shRNAs into NOD/SCID immunodeficient mice to assess the ability of these cells to form tumours in vivo." (PMID 26258887, 2015). "Only one tumour developed from shPARP14-transduced cells was smaller in size and had partially regained PARP14 expression." (PMID 26258887, 2015). "Similarly, in ovarian cancer, PARP14 inhibition suppresses tumor growth by modulating MARylation of receptor for activated C kinase 1 (RACK1) and stress granule formation." (PMID 40741921, 2025). "Recent publications have also demonstrated the tumor-promoting activities of PARP14." (PMID 38612413, 2024). "Similarly, the inhibition of PARP14 has been shown to synergize with anti-PD-1 therapy, improving survival in tumor-bearing mice by enhancing anti-tumor immune responses." (PMID 39062190, 2024). "However, despite being recognized as an oncoprotein, there is limited information available regarding the specific roles of PARP14 in the context of tumor immune evasion, and little is known about the role of ADP-ribosylation in the polarization of TAMs." (PMID 38612413, 2024). "Moreover, PARP14i treatment was more successful than PARP14 knockdown in tumour cells alone in restoring α-PD-1 sensitivity." (PMID 37752135, 2023). "Thus, we found that PARP14 pharmacological antagonism or silencing in tumour cells enhanced STAT1 phosphorylation and expression of STAT1 target gene products, including IRF1 responsible for the expression of many IFNγ signalling genes but also PARP14 itself." (PMID 37752135, 2023). "In conclusion, we propose antagonism of PARP14 with a catalytic inhibitor as a safe and efficacious approach to target high tumour cell intrinsic IFNγ signalling resulting from adaptation to α-PD-1 and thereby restore sensitivity to ICBT in progressing tumours." (PMID 37752135, 2023). "Effector T cell infiltration is enhanced in tumours derived from cells pre-treated with IFNγ in immunocompetent female mice when PARP14 is pharmacologically inhibited or knocked down, while the presence of regulatory T cells is decreased, leading to restoration of α-PD-1 sensitivity." (PMID 37752135, 2023). "PARP14 is involved in the cellular response and signalling pathways of the immune system, in which it regulates the activation of macrophages, and is considered a viable target for treating tumour-related and allergic inflammation." (PMID 36567857, 2022). "The role of PARP14 in DNA repair also suggests its inhibition may sensitise tumours to DNA-damaging chemotherapeutics." (PMID 35096828, 2021). "Elevated expression levels of PARP14 were found in human HCC cell lines as well as primary tumours, but were absent in normal primary hepatocytes and livers, suggesting a pathogenic role for PARP14 in this disease." (PMID 26258887, 2015). "PARP14 inhibitors might also offer therapeutic benefits in other tumor models." (PMID 40741921, 2025). "Therefore, a combined targeted inhibition of STAT1, PARP9, PARP14 and/or DTX3L could increase the efficacy of currently available treatment for prostate, DLBCL and other high-risk tumour types harbouring an increased STAT1 signalling." (PMID 39189367, 2024).
tumor (continued). "Our initial aim was to explore the expression of pro-tumour ADP-ribosyltransferases PARP14 and PARP9/DTX3L particularly in HNSCC, which are characteristically resistant to treatment and PARP9/14 mediated survival might represent a mechanism for increased survival." (PMID 38182103, 2024). "Importantly, PARP14 silencing in IFNγ pre-treated tumours reversed these alterations in the TME." (PMID 37752135, 2023). "Quantitative PCR (qPCR) confirmed a significant increase of mRNA expression for the chemokine ligands Cxcl10 and Cxcl11, supporting our hypothesis that PARP14 inhibition enhances IFNγ signalling in tumour cells and upregulates immune cell infiltration into tumours." (PMID 37752135, 2023). "PARP9, PARP11, PARP13, PARP14, and PARP15: The remaining PARP members with MAR activity exhibit a tumor-promoting role." (PMID 41463260, 2025). "PARP14, frequently overexpressed in hematologic malignancies, reinforces IL-4/STAT6 transcriptional circuits, promoting tumor cell survival and metabolic adaptation." (PMID 41460301, 2025). "Inhibiting PARP14 effectively suppresses EP4 receptor activation, reducing tumor cell proliferation." (PMID 40741921, 2025). "The analysis of OS in patients, stratified by changes in PARPs expression in tumor tissue induced by CRT, revealed a worse survival prognosis when there is a lower change in PARP9 and PARP14 expression (p = 0.025 in both cases)." (PMID 40646573, 2025). "More recently, PARP14 protein levels were found to be increased in HNSC and other tumour types, along with elevated protein levels of its interactors PARP9 and DTX3L." (PMID 39189367, 2024). "In fact, tumor cells from FLs harboring any STAT6MUT (N = 2), and STAT6D419G in particular (N = 1), had significantly higher PARP14 expression compared to STAT6WT tumor cells." (PMID 35851155, 2022). "Moreover, transcriptomic and Q-PCR analyses showed increased expression of Stat1, Zbp1, Parp14, Irf1, and Tifa along with decreased Eif4e2 in the SOR treatment group compared to the tumor control group." (PMID 42194025, 2026). "Treatment with the PARP14 inhibitor RBN012579, by enhancing the IFNγ signalling, re-sensitise these tumours to the PD-1 therapy, establishing PARP14 as an actionable target to reverse IFNγ-driven resistance mechanisms to immune checkpoint blockade therapy (Ref." (PMID 39189367, 2024). "qPCR did not reveal a significant upregulation of Parp14 in bulk-tumour mRNA from α-PD-1 on-treatment tumours compared to control tumours." (PMID 37752135, 2023). "Consistent with α-PD-1 not inducing PARP14 in responding tumours, PARP14i treatment failed to inhibit growth of tumours derived from IFNγ-naïve YUMM2.1 cells nor enhanced the activity of α-PD-1 when both drugs were co-administered." (PMID 37752135, 2023). "Interestingly, PARP14 expression is significantly higher in the HpSC-HCC subtype, which has tumour-initiating features with poor prognosis." (PMID 26258887, 2015). "PARP14 inhibitor treatment would not be efficacious as a monotherapy, as PARP14 antagonism or knockdown did not affect the ex vivo growth of the tumour cell lines we evaluated, nor did monotherapy significantly alter their tumour growth potential, even following chronic IFNγ stimulation." (PMID 37752135, 2023). "However, when we grouped YUMM2.1 and MC38 tumour specimens by the median level of Ifng mRNA (Ifnghigh versus Ifnglow) regardless of treatment, Parp14 expression was significantly higher in Ifnghigh tumours." (PMID 37752135, 2023). "We hypothesised that PARP14 might also act, therefore, as a negative feedback regulator in tumour cells, thereby antagonising IFNγ-stimulated tumour cell immunogenicity." (PMID 37752135, 2023). "Along with PARP14, PARP15 is also overexpressed in B-cell lymphoma; although efforts have been made to develop more selective inhibitors targeting PARP15, the effect of its inhibition on tumor progression has not yet been described." (PMID 41463260, 2025).
tumor (continued). "Interestingly, NK cells were upregulated in tumours derived from chronic IFNγ-pre-treated YUMM2.1 cells, again reversed upon PARP14 knockdown, but there was no dysregulation in gamma-delta T cells." (PMID 37752135, 2023).
infection (15 papers, 2011 to 2025). The state of being infected such as from the introduction of a foreign agent such as serum, vaccine, antigenic substance or organism. "This study presents an analysis of virus replication kinetics as it associates with TMEM154 and PARP14 gene expression in primary skin cells from three goats after in vitro infection with A5 as the known SRLV subtype." (PMID 41497468, 2025). "The expression of cell death and apoptosis-associated genes (e.g., BID, BIRC3 and PARP14) increased throughout the infection, suggestive of increased cell death in response to the infection." (PMID 34452468, 2021). "The observed relationship between expression of TMEM154 and PARP14 and cell permissiveness after SRLV infection suggest their involvement in the infection process, but their utility as susceptibility factors still needs to be verified." (PMID 41497468, 2025). "The study aimed to analyse the expression of TMEM154 and PARP14 genes in primary skin cells of Carpathian goats following infection with the A5 subtype of SRLV." (PMID 41497468, 2025). "PARP14 protein levels increased in the CNS after infection with all three viruses with higher levels at 4 days (P < 0.0001 versus WT/G32S) and lower levels at 6 days (P < 0.05 versus WT, P < 0.0001 versus G32S) in the brains of Y114A-infected mice." (PMID 32047134, 2020). "At 2 days after infection, the brain levels of Parp9, -10, -12, -13, and -14 mRNAs and the spinal cord levels of Parp14 mRNA were higher in Y114A-infected mice than in either WT or G32S-infected mice." (PMID 32047134, 2020). "To further examine the role of PARP14 in N1347A MHV infection, we infected BMDMs harvested from PARP14-/- and PARP14+/- mice." (PMID 31095648, 2019). "Early during infection, viral genomes also associate with factors that have known roles in the recognition or processing of DNA breaks, including RPA1, PARP1, PARP14, and ligase 3 (LIG3)." (PMID 30018111, 2018). "PARP14 is essential for increased IFN-I production in response to infection by coronaviruses that lack ADP-ribosylhydrolase activity – an enzymatic function that reverses host-mediated ADP-ribosylation – or to stimulation with the RNA-mimicking molecule polyinosinic:polycytidylic acid [poly(I:C)]." (PMID 40741921, 2025). "Furthermore, PARP14 also induces IFN-I upon treatment with poly(I:C), a double-stranded RNA mimic, and A549 cells with a deletion of PARP14 were unable to mount a full IFN-I response after infection with MHV coronavirus (mouse hepatitis virus)." (PMID 39055912, 2024). "A subset of genes was significantly translationally upregulated but showed no significant differential expression in the RNA-Seq analysis, reflecting differences of stringency between both methods (i.e., Parp14 and Dhx58) or specific changes in protein stability during infection (i.e., Tmem259)." (PMID 34346771, 2021). "Moreover, many genes exhibited different levels of expression of the various isoforms under infection with one PRRSV strain vs. the other (PARP14, SOCS1, IFIT1, MX1, IFOTM1, RNASEL, PIKSCD and TLR3)." (PMID 24643046, 2014). "Finally, one might predict that PARP14 could reduce immune pathology during infection in vivo owing to its ability repress pro-inflammatory signaling via STAT6." (PMID 35679255, 2022). "Hence, the genes Ccl2, Ch25 h, Ifit3, Il1rn, Il6, Parp14, Ptx3, and Socs3 can be defined as a common core of genes expressed early in response to local infection and inflammation caused by Gram-negative stimuli." (PMID 21338499, 2011). "We found members of this family upregulated by both VN1203 and BC500 infection in ducks (PARP9, PARP10, PARP12 and PARP14)." (PMID 34804075, 2021). "The emergence of a potent and highly specific PARP14 inhibitor, RBN012759, and other knockout cell culture and mouse models will be useful in identifying infections where viral replication, immune signaling pathways, and cell death pathways both in vitro and in vivo are modulated by PARP14." (PMID 35679255, 2022).
bacterial infection (2 papers, 2022 to 2023). "In addition to LPS, PARP14 altered the cellular response to a bacterial infection, as Salmonella typhimurium bacterial load was elevated and IRF-3 target gene expression was reduced in PARP14-depleted cells." (PMID 35679255, 2022).
adenocarcinoma (1 paper, 2022). A common cancer characterized by the presence of malignant glandular cells. "In addition, compound 52 inhibited PARP14auto-MARylation in human primary macrophage and in CFPAC-1 (ductalpancreatic adenocarcinoma cells), the latter characterized by a highendogenous level of PARP14, and the PARP14 engagement was confirmedin an in vivo model." (PMID 35608571, 2022).
neurodevelopmental disorder (1 paper, 2023). A behavioral and cognitive disorder with onset during the developmental period that involves impaired or aberrant development of intellectual, motor, or social functions. "To date, PDPR, LRRC18, and PARP14 have not been associated with neurodevelopmental disorders." (PMID 38025430, 2023).
vascular disorder (1 paper, 2021). A general term used to describe any disease affecting blood vessels]. "Furthermore, in infected macrophages, activation by PARP9 and PARP14 may be hijacked by NSP3’s erasure of ADPr, potentially contributing to the vascular disorders seen in COVID‐19." (PMID 34519429, 2021).
PARP14 also shares sentences with these, for which no sentence is quoted: B cell lymphoma (2 papers); osteoporosis (2); pancreatic adenocarcinoma (2); acute myeloid leukemia (1); allergic asthma (1); arbovirus infection (1); autoimmune disease (1); dermatomyositis (1); diabetic retinopathy (1); emphysema (1); Hypercholesterolemia (1); hyperlipidemia (1); idiopathic pulmonary fibrosis (1); meningioma (1); metabolic disease (1); polymyositis (1); prostate adenocarcinoma (1); prostate tumors (1); psoriasis (1); renal carcinoma (1); renal cell carcinoma (1); stomach adenocarcinoma (1); systemic lupus erythematosus (1); ulcerative colitis (1); urothelial bladder carcinoma (1); uterine infection (1).